CD4 (CD4 molecule)
Diseases named in the same sentence as CD4 in open-access papers (continued):
Sharing a sentence is not in itself a finding about the gene and the disease.
tumor (continued). "Indeed up to 22% of tumor infiltrating CD4 T lymphocytes express FOXP3, suggesting an important contribution of these cells in tumor escape." (PMID 29069740, 2017). "As both CD4+ and CD8+ T cells have been reported to play an important role in immune surveillance, disturbance with the activation of either CD4+ or CD8+ T cells was likely the critical approach for tumor cells to evade the antitumor immunity from the host." (PMID 28099147, 2017). "Local imiquimod treatment induced a systemic antigen-specific CD8 response, but did not prevent the growth of distal tumor because of a lack of CD4 T cell response." (PMID 28620298, 2017). "As controls, donor CD4+ T cells neither expanded nor responded to rhIL-7 after transferring into unconditioned tumor-bearing mice (CD4 and CD4+ rhIL-7)." (PMID 28939858, 2017). "Non-T-cell inflamed MOC2 tumors demonstrated a similar pattern of increased Ly6GhiLy6Cint myeloid cell but not Treg accumulation with tumor progression that was associated with loss of effector CD8+ and CD4+ TIL and NK cell infiltration." (PMID 28915554, 2017). "Moreover, it has been shown that depletion of both CD4+ and CD8+ T cells leads to abrogation of the anti-tumor activity of Lm-LLO-E7." (PMID 28807056, 2017). "CD4+ T cells in PBMC HC made up a significantly lower proportion of CTLA-4+ T cells (24.8 ± 10.7%) than in PBMC HNSCC (69.3 ± 14.6%; p < 0.0001), whereas percentages in PBMC HNSCC and tumor tissue (61.4 ± 16.3%) were comparably high." (PMID 28574843, 2017). "After treatment with anti-CD4 the number of IFNγ+CD8+ T cells in the DLN of mice with control EMT6 tumors was increased ~3-fold relative to PBS treated mice, in keeping with the decreased tumor growth." (PMID 28234914, 2017). "Finally, we looked for possible correlations between tumor microenvironment expression of COX-2, and percentage of CD4 and CD8 tumor infiltrating lymphocytes (TILs) with patient characteristics and clinical outcomes." (PMID 28659181, 2017). "We showed that Lm-LLO-E7 slightly, but not significantly, increased the total number of tumor-infiltrating CD4+ T cells." (PMID 28807056, 2017). "We found that only tumor-infiltrating CD4+ T cells, but not CD8+ T, macrophages or tumor cells express IL-17RB – the receptor for IL-25." (PMID 27909985, 2017). "Our results showed that these mesostrands are valuable as immunoadjuvants for cancer immunotherapy since the mesostrands evoke strong Th1 immune response and anti-cancer immunity, increase CD4+ and CD8+ T cell populations in splenocytes of mice, and inhibit EG7-OVA tumor growth." (PMID 29196724, 2017). "Finally, comparison of CD34+ and CD4+CD8+ healthy donor thymocytes and T-ALL miRNA profiles allowed identifying several novel miRNAs with putative oncogenic or tumor suppressor functions in T-ALL." (PMID 28801656, 2017). "Within the tumor microenvironment of mGITRL-FP-treated CEA.Tg mice, a significant reduction in the percentage of Ki67+/CD44+ CD4+FoxP3- T cells was found, while the frequencies of both CD4+FoxP3+ and Ki67+/CD44+ CD8+ T cells trended downward." (PMID 29088720, 2017). "Our data showed a numerical, but not statistically significant decrease, in tumor CXCR3+ CD4+ and CD8+ T lymphocytes, whereas CCR4+ CD4+ and CD8+ T lymphocytes were present at equal frequencies in tumor and in unaffected tissue." (PMID 29020986, 2017). "However, the choice of T cell adoptive transfer can determine the fate of the tumor and macrophage reprogramming, as CD8+ T cell adoptive transfer is more effective than CD4+ T cell adoptive transfer." (PMID 28769933, 2017). "Intravenous injection of MSCs reduced the presence of CD3+ T lymphocytes, CD4+ T helper cells, CD68+ macrophages, TNF-α-producing, and IL-17-producing cells in the lungs of LLC1-treated mice 28 days after tumor induction." (PMID 28798777, 2017).
tumor (continued). "However, we isolated normal T-cells from healthy donors and co-cultured with MM-BMSCs; the activity of CD4+ T-cells was not affected without the stimulation of tumor microenvironment, which may be the cause of unimpaired inhibitory effect on the proliferation of T-cells." (PMID 28881756, 2017). "Billions of PBMC can reliably be collected by leukapheresis regardless of a patient's tumor type, containing not only CD4+ and CD8+ T-cells, but also monocytes which can be differentiated into professional antigen (Ag)-presenting dendritic cells (DCs)." (PMID 27974697, 2017). "Depletion studies demonstrated that both CD4+ and CD8+ T-cell populations played critical roles in mediating anti-tumor activity, which correlate with the findings of other combination studies that also demonstrate the engagement of both CD4+ and CD8+ T-cell immune responses to reduce tumor burden." (PMID 29207606, 2017). "A similar difference between single and fractionated irradiation was seen for infiltration of the tumor by CD45+, CD4+, CD8+, CD11c, and CD11b immune cells 7 days after irradiation, indicating the recruitment of T cells, DC, macrophages, and possibly NK cells (CD8+ but CD3−)." (PMID 28791250, 2017). "Whereas PBT treatment significantly reduced CT26.CL25 tumor growth in mice possessing a full complement of CD4+ and CD8+ T-cells, PBT treatment had no significant inhibitory effects on tumor growth in mice that had received anti-CD4/CD8 antibodies." (PMID 29137411, 2017). "In contrast, we did not detect any significant upregulation of Grail in tumour-infiltrated CD4+ T cells." (PMID 28798332, 2017). "Interestingly, they also noted that DTA-1 enhanced IL-21 secretion from CD4 T cells in an IL-9-independent manner and proposed that DTA-1 enhances anti-tumor responses through TH9 cell-derived IL-9 and, possibly, IL-21." (PMID 27832300, 2017). "Depletion of CD3+, but not CD4+ subsets in HPD1NR subcutaneous tumor-bearing hamsters had a significant detrimental impact on treatment efficacy suggesting that Ad-TD-nsIL-12 acts via a CD3+ CD4− (CD8+) mechanism to eliminate tumors." (PMID 29123084, 2017). "In our study, the increased frequency of neutrophils and intratumoral CD4+/CD8+ lymphocytes correlated with the inhibition of tumor growth, suggesting that PAFR may be involved in the recruitment of these cells into the tumor stroma." (PMID 29445756, 2017). "The number of CD4+ T cells in the tumor bed was not significantly changed while the number of CD8+ T cells in the tumor bed was significantly increased." (PMID 28747781, 2017). "Furthermore, durable clinical responses were obtained when PBMC-derived tumor-reactive T cells, comprising almost exclusively clonally expressed neoepitope-specific CD8+ and CD4+ T cells, were infused." (PMID 28959257, 2017). "CD4+CD25− CAR T cells lysed CEA+, LS174T, and SW948 tumor cells with high efficiencies." (PMID 28850063, 2017). "Flow cytometry analysis of splenocytes revealed a substantial difference in the percent of CD4+ and CD8+ T cells in HBZ tumor cell transplanted mice (1.6 ± 0.7, 6.3 ± 7.1, n = 3) versus PBS controls (0.36 ± 0.12, 0.12 ± 0.03, n = 3), indicating CD4 and CD8 T cells are transplantable." (PMID 29050201, 2017). "Our above findings that alum-CpG-HH2-NY vaccine was able to enhance humoral immunity, induce NK cell activity and activate CTLs activity suggest that CD4+ T, NK and CD8+ T cells may play an important role in anti-tumor immunity." (PMID 28515346, 2017). "Overall, our findings support reports of tumour‐specific CD4+ T cells displaying a Th1 phenotype, although we did not formally rule out the production of Th2 type cytokines." (PMID 27324616, 2017). "Increased numbers of IFN-γ expressing CD8+ T cells were seen in the DLN of EMT6 though not EMT6siCD200 tumor-bearing mice following treatment with anti-CD4, supporting a role for such cells in host resistance." (PMID 28234914, 2017).
tumor (continued). "In the human HLA A2‐restricted NY‐ESO‐1157–165 tumour system, transduced CD8+ T cells expressing TCRs with a binding dissociation constant (KD) of 84 nM were found to be cross‐reactive, while transduced CD4+ T cells only displayed off‐target effects at considerably higher affinities." (PMID 27324616, 2017). "Although aGITR administered as a monotherapy or as a dual therapy reduced Tregs, we did not observe improved tumor suppression or synergy when CD4 depletion was combined with Vax/aGITR/aPD-1 therapy." (PMID 28388572, 2017). "Indeed, IL-27 has been shown to drive upregulation of HLA-I also in chronic eczema keratinocytes that produced IL-27, but it promoted PD-L1 expression in different cell types including CD4+ and CD8+ T cells, monocytes, DC and tumor cells." (PMID 28456791, 2017). "Therapeutic induction of effector CD4 T cell responses against EBV antigen to fight malignancies demonstrate promise in animal models; effective killing of virus-induced tumor cells following treatment with a CD137 agonist was seen in CD8 T cell-deficient mice." (PMID 28167943, 2017). "In present study, we compared the expression of PD-1+ and Tim-3+ on CD4+/CD8+ T-cells in blood circulation, tumor, and paraneoplastic tissues from patients with GC, and further tested the changes of IFN-γ production on T-cells after in vitro blockade of PD-1+ and/or Tim-3+ pathways." (PMID 29213216, 2017). "Since T‐regs numbers increase as a result of tumor progression, we looked at numbers of CD4+, CD25+, FoxP3+ T‐regs to see if the noted increases of CD4+ T‐cells resultant of subcutaneous tumors might be due to an increase in T‐regs." (PMID 28250928, 2017). "The mice receiving either anti-CD8 Ab or anti-CD4 Ab died earlier from tumour progression than those receiving the dual treatment without depletion." (PMID 28345650, 2017). "However, coordination of less differentiated CD4+ Th1 cells and CD8+ CTLs is important for the induction of complete tumour regression." (PMID 29114389, 2017). "Very few CD3+ (either CD4 and CD8) T cells were found within or surrounding the tumour." (PMID 28276463, 2017). "Thus knocking down PITPNM3 in CD4+ cells reduced TI Tregs and enhanced TI CD8+ T cells, promoting anti-tumor immunity and tumor control." (PMID 28290464, 2017). "Moreover, the Th1 profile of the response favored the migration of IFNγ-producing CD4+ and CD8+ T cells at the tumor site, eventually contributing to the overall protective activity of vaccination." (PMID 29164053, 2017). "In contrast to HIF-1α-deficient tumor-infiltrating CD8+ T cells, however, PD-1 expression in VEGF-deficient tumor-infiltrating lymphocytes (TILs) is unaffected and there are no changes in FOXP3 expression levels in infiltrating CD4+ T cells." (PMID 29136509, 2017). "Other non-glial intracranial tumors, including meningioma and metastatic non-small cell lung cancer, showed however no accumulation of CD4+CD56+ in the tumor." (PMID 28791027, 2017). "Depletion of CD8+ T cells entirely abrogated the anti-tumor immunity of alum-CpG-HH2-NY, whereas depletion of CD4+ T cells slightly diminished the anti-tumor immunity and showed no statistical difference relative to IgG2b treatment (control)." (PMID 28515346, 2017). "In most cases, CD4+CD25+ Treg cells suppress the anti-tumor immune response in 2 aspects: one mode is via cells in the tumor-draining regional lymph node; the other mode is through the tumor tissue." (PMID 28796055, 2017). "Although DC group significantly inhibited tumor growth, the frequencies of CD4+ and CD8+ T cells and their activation status did not changed compared to the control group." (PMID 28404904, 2017). "Further, we observed a decrease in the expression of the activating co-stimulatory molecule 4-1BB up to 5-fold on CD4+ T cells and 2-fold on CD8+ T cells in the presence of spheroid polarized MDMs in comparison to activated T cells in co-culture with tumor cells and fibroblasts alone." (PMID 28750018, 2017).
tumor (continued). "Previous studies have shown that CCR4+ T cells can be recruited to the GBM microenvironment (Ti-CCR4+ T cells), and our data further indicated that CD4+CCR4+ T cells were relatively specifically enriched in GBM and more abundant in the tumor microenvironment than those in the peripheral blood." (PMID 29312296, 2017). "This led to BL being designated an AIDS-defining illness; importantly, however, the tumour typically develops early in the course of HIV infection, coincident with symptoms of persistent generalized lymphadenopathy and before circulating CD4+ T cell numbers begin to fall." (PMID 28893938, 2017). "TCR+CD4+ and CD8+ donor-derived T cells were present in both spleens and tumor grafts." (PMID 28147310, 2017). "Tumour growth was dramatically suppressed by the tumour-cell-vaccinated DCs; however, this antitumor effect was strongly attenuated by the cooperation of lnc-EGFR-infected CD4+ T cells, but was rescued by EGFR knockdown or lnc-EGFRΔR1." (PMID 28541302, 2017). "The percentage of PD-L2+ TIL, as a continuous variable in both CD4+ and CD8+ TIL, was positively correlated with tumor size and IHC scores for %Ki67, %stromal TIL, %global TIL, %intratumoral TIL, TLS, %CD4+, and %CD8+ despite a very low proportion of positivity." (PMID 29163490, 2017). "Yet, within the PDAC tumor microenvironment, CD40 could override the demand of the CD4+ helper cells for activating cytotoxic CD8+ T cells." (PMID 28753978, 2017). "Since YM-2A directly activates antigen-presenting cells in vitro and increased the numbers of splenic DCs and T cells in vivo, we next assessed whether oral administration of YM-2A can induce IFN-γ expression by CD4+ and CD8+ T cells in tumor-bearing mice." (PMID 28278221, 2017). "Interestingly, although we originally transferred the same numbers of CD4+ Th1 cells and CD8+ CTLs, most of the cells that persisted after clearance of tumour were CD8+ CTLs." (PMID 29114389, 2017). "Although the combination therapy augmented the pool of CD4+ T-cells in 4T1 tumor-bearing mice, it did not demonstrate any proliferative effects on CD8+ T-cell populations located in the lung and spleen." (PMID 29207606, 2017). "In this study, we demonstrated that mice cured of tumors by combination therapy, consisting of the transfer of ex vivo—expanded CD4+ T cells after irradiation and Treg depletion, successfully rejected the challenge of MCA205 tumor cells 90 days after the first inoculation of MCA205 cells." (PMID 28854279, 2017). "This was also associated with a shift from Th2 and Th17 to Th1 in the form of cytokine and switching of antibody class, which appears to be mainly due to the selective depletion of induced T regulatory cells (CD4+CD25+FoxP3+ CD39+FR4+GITR+CD127−) in blood, spleen, lymph node, and the tumor." (PMID 28447025, 2017). "This was not simply due to diminished PD-1 receptor expression, because PD-1 amounts were even enhanced in Cblb-deficient CD4+ and CD8+ T cells in vitro or not significantly altered on Cblb-deficient tumor infiltrating T cells, respectively." (PMID 28611299, 2017). "Although the overall number of T cells remained similar in MK2ΔCD11c and WT dLN upon LPS + tumour lysate immunization, the ratio of CD8+/CD4+ cells was significantly altered, favouring the priming of CD8+ cytotoxic T lymphocytes (CTLs) upon MK2 knock-out in CD11c+ DCs." (PMID 28924177, 2017). "Moreover, LAG3 signaling contributes to CD4+ regulatory T cell suppression of autoimmune responses and CD8+ T cells tolerance to self and tumor antigens." (PMID 29383101, 2017). "Treatment of MOC1 tumor-bearing mice with CTLA-4 mAb plus gMDSC depletion in the presence of cellular depleting mAbs revealed that tumor rejection is dependent upon CD8+ but not CD4+ or NK cells." (PMID 28915554, 2017). "CD4+ T cells release immunoregulatory cytokines such as IFN-γ and TNF that may induce cytolytic T cell responses in tumours." (PMID 28322245, 2017).
tumor (continued). "Further, when Spearman’s correlation coefficient (rs) was calculated, there was significant positive correlation between number of survival days and the ratio of peripheral CD4+ cells (rs = 0.662, p < 0.01) or CD8+ cells (rs = 0.650, p < 0.01) at 2 weeks after tumor inoculation." (PMID 28864944, 2017). "Loss of responsiveness to IFN-γ provides an immune escape mechanism for many human tumors, yet tumor sensitivity to IFN-γ was not required for inhibition of tumor angiogenesis or infiltration of CD4+ and CD8+ T cells to the tumor site in response to Lm-LLO-E7 in preclinical models." (PMID 28588899, 2017). "Interestingly, activation of multiple TLRs using a combination of TLR3, TLR4, and TLR7 ligands resulted in tumor rejection in 50% of mice in a B16-OVA tumor model with poor immunogenicity, increasing innate immunity and CD8+ and CD4+ T-cell responses." (PMID 29190881, 2017). "First, the depletion of CD4+ and CD8+ T cells entirely abrogates anti-CD27 activity, but not combination therapy, signifying that in combination, alternative, synergistic mechanisms of anti-tumor activity come into play." (PMID 29198913, 2017). "However, both CD4 and CD8 tumor-infiltrating lymphocytes (TILs) tend to be suppressed and, hence, unable to control tumor growth." (PMID 29234325, 2017). "RT in combination with the anti‐PD‐L1 also significantly reduced infiltration of CD4+CD25+FOXP3+ T regulatory cells, further supporting the notion that PD‐L1 checkpoint inhibition together with RT can counteract the immunosuppressive tumor environment." (PMID 27932443, 2017). "Among the immune cells, CD8+ T cells and CD4 helper T cells 1 (TH1), NK cells, M1 macrophages, dendritic cells work against the tumor while regulatory T cells (Treg), M2 macrophages, myeloid derived suppressor cells (MDSC), CD4 helper T cells 2 (TH2) cells promote tumor growth." (PMID 27886124, 2016). "Interestingly, the proportion of different lymphocyte subpopulations was altered in tumors in which SK1 was inhibited, with a significant increase of NK cells as well as T-cells (Thy1+) such as CD4+ and CD8+ tumor-infiltrating lymphocytes." (PMID 27708249, 2016). "This suggests that the infiltration of CD4+ T cells into the tumor leads to the preferential outgrow of MHC class II negative mutated cells." (PMID 27060000, 2016). "Accordingly, AMD3100 did not affect the percentage of tumor-infiltrating CD8+ or CD4+ T-cells, which were decreased in Bay60-6583-treated mice compared to controls." (PMID 27590504, 2016). "Similarly, mice with more than 1% of human CD4+ and CD8+ T cells in tumors presented lower tumor burden." (PMID 27409425, 2016). "In this regard, when CD11b+ MDSC were depleted from L-selectinlo splenic populations from 4T1-bearing mice we observed complete L-selectin recovery on CD4+ and CD8+ T cells within four days after culture or post-adoptive transfer into non-tumor bearing recipient mice." (PMID 27929373, 2016). "Moreover, the tumor protective effects of P2Et treatment were abolished in immunodeficient mice, and partially lost after CD4 and CD8 depletion, indicating that P2Et's anti-tumor activity is highly dependent on immune system and at least in part of T cells." (PMID 27253407, 2016). "Other researchers have reported that regulatory DCs may suppress the proliferation and activation of CD4+CD25- and CD8+CD25- T cells, resulting in immune suppression and thus inhibition of an immune attack on tumour cells." (PMID 27355390, 2016). "Interestingly and in contrast to tumor-free mice, tumor-bearing CSC-mice 9 days after termination of CSC/SHC still showed an increased Treg cell proportion in the CD4+ T cell population similar to what has been observed directly after termination of CSC." (PMID 27391954, 2016). "The negative correlations between IL-10-expressing B cells and CD4+ cytotoxic T cells were also observed in tumor-infiltrating cells." (PMID 27136203, 2016).